NLRP3 (NLR family pyrin domain containing 3)
Diseases named in the same sentence as NLRP3 in open-access papers (continued):
Sharing a sentence is not in itself a finding about the gene and the disease.
viral pneumonia (7 papers, 2020 to 2026). Inflammation of the lung parenchyma that is caused by a viral infection. "Innate immune cells, mainly, macrophages with shortened telomeres, exhibited hallmarks of cellular senescence, mitochondrial distress, and aberrant activation of STING and NLRP3 inflammasome pathways, which predisposed mice to severe viral pneumonia during commonly mild infections." (PMID 35313074, 2022). "This study investigates the mechanisms by which the Hippo signaling pathway interacts with NLRP3-driven NETosis in macrophages, particularly in the context of exacerbated viral pneumonia." (PMID 40659620, 2025). "Given its pivotal role in bacterial or viral pneumonia, targeting the NLRP3 inflammasome presents a promising therapeutic strategy." (PMID 40218944, 2025). "Patients with viral pneumonia showed increased NLRP3 and IL-1β expression in monocyte-derived macrophages compared to healthy controls." (PMID 40659620, 2025). "Our findings reveal a novel Hippo-NLRP3-IL-1β-NETs axis that contributes to viral pneumonia pathogenesis." (PMID 40659620, 2025). "NETosis aggravates virus-induced lung injury and is increased in viral pneumonia by regulating the Hippo pathway via the NLRP3/IL-1β axis." (PMID 40659620, 2025). "The Hippo pathway was activated in monocyte-macrophages from patients with viral pneumonia, and both NLRP3 and IL-1β proteins were highly expressed in these patients compared to those in healthy volunteers." (PMID 40659620, 2025). "In viral pneumonia, NLRP3 functions dually as a mediator of antiviral defense and a driver of immunopathology." (PMID 40860873, 2025). "By identifying the Hippo pathway and NLRP3 as potential therapeutic targets for modulating excessive inflammation and NETosis, our work offers promising directions for developing more effective treatments for viral pneumonia." (PMID 40659620, 2025). "Furthermore, the intricate relationship between the Hippo pathway and various signaling cascades, particularly those involving NLRP3, underscores the complexity of immune regulation in viral pneumonia." (PMID 40659620, 2025). "The interplay between YAP/TAZ and NLRP3 may represent a pivotal axis in this context, suggesting that targeting this interaction could enhance therapeutic strategies against viral pneumonia." (PMID 40659620, 2025). "In addition, NLRP3 is a key regulator of infectious inflammation, particularly during bacterial and viral pneumonia." (PMID 33128438, 2020). "In addition to the NLRP3 inflammasome, other inflammasomes may also be involved in the regulation of immune responses during viral pneumonia." (PMID 40659620, 2025).
AA amyloidosis (6 papers, 2017 to 2025). Secondary amyloidosis is a form of amyloidosis, that complicates chronic inflammatory disorders (mainly rheumatoid arthritis) and is characterized by the aggregation and deposition of amyloid fibrils composed of serum amyloid A protein, an acute phase reactant. "Here we report that ASC, the central component of the NLRP3, NLRC4 and AIM2 inflammasomes, coaggregates with SAA in tissues of patients with inflammation-associated AA amyloidosis." (PMID 39080493, 2024). "Two patients developed AA amyloidosis, which previously has only been reported in CAPS in association with life-long germline NLRP3 mutations." (PMID 29163488, 2017). "AA amyloidosis is a life-threatening complication of CAPS, which hitherto has only been reported in patients with germline NLRP3 mutations." (PMID 29163488, 2017). "Most NLRP3-AID patients are highly responsive to IL-1–targeted therapies, especially on cutaneous, ocular, and articular features, and prevention of inflammatory amyloidosis." (PMID 38530241, 2024).
adult-onset Still disease (6 papers, 2019 to 2025). A rare inflammatory multisystem disorder characterized clinically by fever of unknown origin, arthralgia or arthritis, hyperleucocytosis, and typical skin rash. "NETs derived from adult-onset Still’s disease reportedly activate the NLRP3 inflammasome within macrophages." (PMID 41395250, 2025). "NETs-derived extracellular DNA induces NLRP3 inflammasome in adult-onset Still’s disease (AOSD) and high-mobility group box 1 (HMGB1), and LL37 can drive SLE." (PMID 36361646, 2022). "Another 2017 paper showed that PBMCs taken from individuals with adult-onset Still’s disease (AOSD; an autoinflammatory condition), when compared to healthy controls, displayed elevated levels of NLRP3 mRNA and decreased expression of NLRP7, NLRP2, and NLRP12." (PMID 36298668, 2022). "As well, patients with adult-onset Still’s disease (AOSD) presented with higher levels of circulating NETs compared to controls, which contributed to the NLRP3 inflammasome and macrophage activation, finally increasing the release of pro-inflammatory cytokines." (PMID 31963447, 2020).
alcoholic steatohepatitis (6 papers, 2016 to 2022). "Recently, it was demonstrated that the NLRP3 inflammasome was involved in the development of chronic liver diseases, such as alcoholic steatohepatitis and NAFLD." (PMID 30893931, 2019).
bacterial pneumonia (6 papers, 2016 to 2025). Acute infection of the lung parenchyma caused by bacteria (e.g., Streptococcus pneumoniae, Haemophilus influenzae, Chlamydia pneumoniae, Mycoplasma pneumoniae, and Legionella pneumophila). "In conclusion, CME can play a therapeutic role in LTA-induced inflammation in MH-S cells via TLR2/NF-κB/NLRP3, and may serve as a potential drug for bacterial pneumonia caused by Gram-positive bacteria." (PMID 37958501, 2023). "In conclusion, the treatment of bacterial pneumonia by UC-MSCs can be achieved by down-regulating the expression of NLRP3, TLR4 and NF-kB mRNA and protein." (PMID 40271073, 2025).
Brain atrophy (6 papers, 2021 to 2026). Partial or complete wasting (loss) of brain tissue that was once present. "In human MCI and AD retinas, we further delineate a Chlamydia pneumoniae–linked NLRP3 inflammasome axis that converges on IL1β processing, apoptosis, and pyroptosis, and retinal and brain atrophy." (PMID 41571675, 2026). "We found that retinal NLRP3 and Casp1 were very strongly correlated with retinal atrophy, an index of retinal thickness from inner limiting membrane to outer limiting membrane (r = 0.82–0.86, p<0.001–0.0001), whereas these markers had moderate correlation with brain atrophy (r = 0.41–0.47, p<0.05)." (PMID 40667156, 2025). "In addition, the brain atrophy and infarct size of TRPV1 KO mice after HI were decreased, which was found to be closely related to suppressing the activation of astrocytes and releasing astrocyte-derived IL-1β, mainly via JAK2-STAT3 signaling and activation of the NLRP3 inflammasome." (PMID 34691200, 2021).
brain hemorrhage (6 papers, 2020 to 2025). "We found that collagenase-induced brain hemorrhage and oxidative stress and promoted neuroinflammation (via NLRP3 inflammasome), which aggravated brain damage." (PMID 38981960, 2025). "NLRP3 mRNA methylation plays a crucial role in regulating cell apoptosis in brain hemorrhage." (PMID 40083546, 2025). "Therefore, studying the role of NLRP3 inflammasome in related mechanisms after intracranial hemorrhage will provide a new strategy for its treatment." (PMID 34526897, 2021). "It is worth noting that many important issues regarding the pathogenesis of NLRP3 inflammasomes in intracranial hemorrhage need to be further studied and elucidated, such as the activation mechanism and effects of NLRP3 inflammasomes in the late stage of cerebral hemorrhage." (PMID 34526897, 2021). "VSIG4 also attenuates NLRP3 via the JAK2-STAT3-A20 pathway and ameliorates neuroinflammation after brain hemorrhage in mice." (PMID 37153746, 2023).
brain inflammation (6 papers, 2018 to 2025). "It has been confirmed that 25-HC can activate the NLRP3 inflammasome, causing brain inflammation, and has been identified as an integrin ligand capable of directly inducing proinflammatory responses in macrophages." (PMID 40760662, 2025). "We focused on the effects of the NLRP3 inflammasome on peripheral inflammation and brain inflammation, which was the most representative inflammasome responsible for recognizing exogenous and endogenous danger signals." (PMID 38393047, 2024). "The knockdown of SPATA2 leads to the activation of P38MAPK and NLRP3 inflammasome and the enhancement of NF-κB signaling, indicating that SPATA2 plays a protective role against brain inflammation induced by ischemia/reperfusion injury." (PMID 37528851, 2023). "This study further proved the anti-neuroinflammatory effects of savinin at the in vivo level for the first time, that is, savinin inhibits brain inflammation, and these effects are related to both MAPK/NF-κB and NLRP3 pathways." (PMID 36838564, 2023).
cerebral small vessel disease (6 papers, 2022 to 2025). Cerebral small vessel disease is the term currently used to pathological processes that affect the brain parenchymal circulation (arterioles, capillaries, and veins). "Cerebral small vessel disease (CSVD) may benefit from anti-inflammatory therapy, as age-related inflammation—mediators such as TNF, caspase-1, IL-1β, and the NLRP3 inflammasome—is considered a risk factor." (PMID 40017533, 2025).
chronic myeloid leukemia (6 papers, 2019 to 2025). "Studies have shown that TKIs, especially imatinib in the treatment of chronic myeloid leukemia, through off-target effects, activate NLRP3 specifically in primary myeloid cells." (PMID 40678003, 2025). "Interestingly, NLRP3 and IL-1β mRNA expression levels were shown to be decreased, while IL-18 mRNA expression levels were shown to be increased in chronic myeloid leukemia (CML) compared to controls." (PMID 38397043, 2024).
chronic prostatitis (6 papers, 2017 to 2024). An infectious or non-infectious chronic inflammatory process that affects the prostate gland. "P2X7R agonist, antagonist, NLRP3 inhibitor, and disulfiram were used to explore the roles of the P2X7R-NEK7-NLRP3 axis in prostate epithelial cell pyroptosis and chronic prostatitis development." (PMID 38993566, 2024). "Meanwhile, extracorporeal shock wave therapy (ESWT) was reported to improve chronic prostatitis by repressing NLRP3 inflammasome and alleviating apoptosis." (PMID 38993566, 2024). "Herein, roles of P2X7R-NEK7-NLRP3 axis-mediated prostate epithelial cell pyroptosis in chronic prostatitis were explored, and we found that NLRP3 inflammasome was involved in P2X7R-mediated prostate epithelial cell pyroptosis." (PMID 38993566, 2024). "In the urological field, there are reports of NLRP3 involvement in prostatitis, in bladder denervation that develops after bladder outlet obstruction by benign prostatic hyperplasia, and in diabetic bladder dysfunction." (PMID 35563427, 2022). "The selected expression of NLRP3 and NLRP12 inflammasomes was validated, and the clinical association was evaluated in human prostate archival tumor tissues." (PMID 28663562, 2017). "Because P2X7R and NLRP3 inflammasome were mainly expressed in the prostate epithelial cells of EAP mice, we used LPS-primed human prostate epithelial cells to mimic prostatitis to further validate the effects of P2X7R/NLRP3 pathway on the development of chronic prostatitis." (PMID 38993566, 2024). "Our team previously demonstrated that alcohol exacerbated the progression of chronic prostatitis via upregulating the NLRP3 inflammasome 13, and melatonin could alleviate chronic prostatitis development via the SIRT1/NLRP3 pathway." (PMID 38993566, 2024). "Hence, P2X7R was identified as a new upstream regulator of NLRP3 in chronic prostatitis, and P2X7R-mediated NLRP3 inflammasome activation could induce Th17 cell differentiation and promote chronic prostatitis development." (PMID 38993566, 2024). "However, the upstream regulator of NLRP3 in chronic prostatitis development is not fully elucidated, and exploring the upstream regulator of NLRP3 may provide novel targets for chronic prostatitis treatment." (PMID 38993566, 2024). "Hence, NLRP3 inflammasome could exacerbate chronic prostatitis, and targeting NLRP3 inflammasome was warranted for chronic prostatitis treatment." (PMID 38993566, 2024). "In this study, we identified P2X7R as an upstream of NLRP3, and that suppression of the P2X7R-NLRP3 axis could attenuate EAP development, which may be a therapeutic approach for chronic prostatitis treatment." (PMID 38993566, 2024). "In our previous studies, we found that NLRP3 was involved in alcohol-exacerbated chronic prostatitis 13 and melatonin-attenuated chronic prostatitis 14, while the upstream of NLRP3 was not fully elucidated in chronic prostatitis development." (PMID 38993566, 2024). "Although the roles of pyroptosis in inflammatory diseases have been clarified a lot, pyroptosis in chronic prostatitis is unclear, and whether P2X7R/NLRP3 could modulate pyroptosis to exacerbate chronic prostatitis development is unknown and deserves further study." (PMID 38993566, 2024).
colorectal tumors (6 papers, 2019 to 2024). "In the colorectal carcinogenesis model, fewer colorectal tumors were observed in both NLRP3-deficient and glyburide-treated groups." (PMID 39519191, 2024). "In contrast to the present study, previous reports have indicated that NLRP3 deficiency leads to colorectal tumor progression." (PMID 39519191, 2024). "Activation of NLRP3 and release of IL-1β was also reported to cause overproduction of 5-hydroxytryptamine in colorectal tumors, which accelerates CAC development." (PMID 38898209, 2024). "In conclusion, the findings of this study support the possibility that inhibition or KO of NLRP3 suppresses colorectal tumor development caused by chronic inflammation, although deletion of NLRP3 may exacerbate acute colitis." (PMID 39519191, 2024). "In addition, NLRP3 inhibition also increased the population of F4/80+ macrophages in colorectal tumors, similar to what was observed in GSDMD knockout mice." (PMID 38898209, 2024). "Therefore, NLRP3 inflammasome plays an important role in the occurrence and development of colorectal tumors." (PMID 34955826, 2021). "Therefore, the down-regulation of inflammatory cytokines due to NLRP3 deficiency or inhibition may result in the inhibition of COX2 signal activation, subsequently leading to the suppression of colorectal tumor development." (PMID 39519191, 2024). "Consistently, ablation of GSDMD in colorectal tumors did not result in any change in the activation of caspase 1, or IL-1 family cytokines or formation of NLRP3 or ASC specks." (PMID 38898209, 2024). "We found decreased levels of NLRP3 protein and activated GSDMD in large colorectal tumors compared to small ones, suggesting the inefficiency of bacteria and their products reaching the core of large colorectal tumors." (PMID 38898209, 2024).
coronary artery stenosis (6 papers, 2016 to 2024). "Genetic investigation of coronary artery disease patients also found that patients carrying the G allele of NLRP3 rs10754558 had more severe coronary artery stenosis and higher levels of serum IL-1β." (PMID 35000611, 2022). "This indicated that patients carrying G allele of NLRP3 rs10754558 had more severe coronary artery stenosis." (PMID 27110561, 2016). "With the G allele of NLRP3 rs10754558 enhancing the mRNA stability of NLRP3, it increases the mRNA expression of this inflammasome receptor, potentially contributing to the pathophysiology of coronary artery stenosis." (PMID 35000611, 2022). "Patients carrying G allele of NLRP3 rs10754558 had more severe coronary artery stenosis." (PMID 27110561, 2016). "The PCA revealed that the expression signatures of RMRP, MIAT, NTT and the expression profiles of MALAT1, HSPA1A, and NLRP3 moderately differed between the thallium stress test (+) CAG (–) and thallium stress test (+) CAG (+) groups regardless of significant coronary artery stenosis." (PMID 37238718, 2023).
demyelination (6 papers, 2018 to 2023). "It has been reported that astrocyte, microglia and the NLRP3 inflammasome are activated in demyelination animal models." (PMID 34407865, 2021). "In a chlorpromazine- (CPZ-) induced demyelination mouse model, the progesterone treatment group exhibited a decrease in neurological behavioral deficit scores accompanied by decreased levels of NLRP3 inflammasomes." (PMID 29849483, 2018). "This research suggests that NLRP3 inflammasomes are involved in the pathogenesis of the CPZ-induced demyelination mouse model." (PMID 29849483, 2018). "Similarly, we found caspase-1, GSDMD, NLRP3 and IL-1β mainly localize in microglia, suggesting microglia as the dominating cell type that undergo pyroptosis in our LPC-induced demyelination model." (PMID 36803990, 2023).
diffuse large B-cell lymphoma (6 papers, 2021 to 2025). "For example, data from patients with diffuse large B-cell lymphoma (DLBCL) have shown that NLRP3 activation upregulated PD-L1 and reduced the proportion of cytotoxic T cells." (PMID 34769275, 2021).
Dyskinesia (6 papers, 2018 to 2023). A movement disorder which consists of effects including diminished voluntary movements and the presence of involuntary movements. "Our results demonstrated that NLRP3 knockdown in the SNc region significantly improved MPTP‐induced dyskinesia, DA neuronal loss and microglia activation in vivo." (PMID 36199191, 2022). "Microglial NLRP3 inflammasome activation induces dopaminergic neuron death and subsequent dyskinesia in PD, while dopamine can significantly reduce NLRP3-dependent inflammasome activation in mixed glial cells stimulated by NLRP3 agonists." (PMID 36235760, 2022). "We provide convinced evidence that miR-30e improves neuronal damage, neuroinflammaiton and dyskinesia via negatively regulating Nlrp3 expression and inhibiting NLRP3 inflammasome activation in MPTP-induced PD mice model." (PMID 29274035, 2018). "During the repair of the injured mucociliary epithelium in the ALI system, silica-induced NLRP3 inflammasome activation led to either MUC5AC or MUC5B overproduction, multiciliogenesis, and ciliary disorientation, structural defects and dyskinesia." (PMID 37063430, 2023).
enteropathy (6 papers, 2016 to 2023). "A recent study suggested that NLRP3 inflammasome activation and associated IL-1β release play a key role in NSAID-induced enteropathy." (PMID 30555323, 2018). "We previously reported that P31-43 induces additional pro-inflammatory effects on Caco-2 cells, namely NLRP3 inflammasome activation and NF-κB p65 translocation into the nucleus with consequent increased IL-1β production and upregulation of IL-15, a known mediator of the gliadin-induced enteropathy." (PMID 30981209, 2019). "Because the NLRP3 inflammasome has previously been shown to be activated by AIEC strains in vitro and in NSAID enteropathy, we analyzed its activation by AIEC/NSAID in our model." (PMID 36656595, 2023). "In parallel, the enteropathy induced by p31-43 in vivo did not occur in the absence of NLRP3 or caspase 1 and was inhibited by administration of the caspase 1 inhibitor Ac-YVAD-cmk." (PMID 30761127, 2019).
esophageal squamous cell carcinoma (6 papers, 2022 to 2025). Esophageal squamous cell carcinoma (ESCC) is a type of esophageal carcinoma (EC) that can affect any part of the esophagus, but is usually located in the upper or middle third. "The overexpression of NLRP3 in esophageal squamous cell carcinoma cell lines markedly promoted migration and invasion." (PMID 36766797, 2023). "For instance, the overexpression of NLRP3 inflammasome stimulated proliferation, migration, and invasion of esophageal squamous cell carcinoma (ESCC) in vitro." (PMID 38026959, 2023). "For example, in esophageal squamous cell carcinoma, piperlongumine inhibited tumorigenesis by triggering NRF2/ROS/TXNIP/NLRP3-dependent pyroptosis." (PMID 40125551, 2025). "Furthermore, research has shown that Fn activates NLRP3 in ESCC cells (esophageal squamous cell carcinoma), which increases MDSCs and significantly reduces the therapeutic efficacy of cisplatin chemotherapy." (PMID 39860963, 2024).